ENSG00000206849
Synonyms: LOC124900362
Gene: Small nucleolar RNA gene on chromosome 15 (31,928,303 to 31,928,434, forward strand). Ensembl gene ENSG00000206849.
Gene Ontology:
Biological process: RNA processing
Cellular component: nucleolus
Homologues: Paralogues in human: SNORA18 (92% identical).